GLI1 (GLI family zinc finger 1)
Diseases named in the same sentence as GLI1 in open-access papers (continued):
Sharing a sentence is not in itself a finding about the gene and the disease.
tumor (continued). "Activation of GLI1 and GLI12 leads to upregulation of many pro-proliferative, pro-survival and pro-angiogenic genes, leading to tumor growth and therapeutic resistance." (PMID 26891329, 2016). "Gli-1 additionally stimulates SOX9 transcription, which provides an explanation for the observed significant increase of SOX9 in tumor cells." (PMID 27281617, 2016). "GLI1 and AXIN2 were upregulated in the primary tumor and in two inoculation metastases compared to normal brain." (PMID 27825128, 2016). "The expression of Oct4, Sox2, Gli1, CD44, CD133, p-AKT, and p-ERK was positively correlated with a more aggressive tumor phenotype and poorer overall prognosis." (PMID 26769843, 2016). "Both tumor types exhibited classic histology, and similar expression patterns for expected Shh-MB neural markers (Atoh1, TUBB3 and GFAP) and Hh target genes (Gli1, Mycn and Ccnd1)." (PMID 27823583, 2016). "The human tumor data paralleled our cell line findings in that there was high PTCH1, SMO, GLI2, and GLI3 mRNA, but low GLI1 mRNA." (PMID 27793025, 2016). "SHH-mediated GLI1 activity lead to the transcriptional activation of the cysteine-rich angiogenic inducer 61 (CYR61); silencing CYR61 resulted in reduced tumor vasculature of SHH-driven xenografts." (PMID 26988232, 2016). "We first examined p-AKT in the 126 tumor tissues and found that there were 24 low p-AKT patients among 30 low Gli1 patients and 53 high p-AKT patients among 96 high Gli1 patients (χ2 = 11.38, P < 0.05)." (PMID 27863385, 2016). "We were able to demonstrate that GANT61 alone or in combination with IR significantly reduced gene expression of the main Hh target genes GLI1, GLI2 and PTCH1 in the tumor cells, but also in the surrounding stroma." (PMID 27713179, 2016). "Many studies on the roles of the HH signaling pathway in NSCLC suggested that GLI1 and GLI2 play central roles in tumor progression, tumor metastasis, and CSC maintenance." (PMID 28105432, 2016). "We found that 57.8% (59/101), 71.3% (72/101), and 57.8% (59/101) GC tumour specimens stained positively for CD44, Shh, and Gli1 protein, respectively." (PMID 26839535, 2016). "We were the first to show SHH gene expression in human MPM tumor tissues along with increased expression levels of HHIP and GLI1." (PMID 26184317, 2015). "Positive expression of HIF-1α was found in 57.7% of all the tumor samples from all clinical stages, and the degree of positive staining for SHH, PTCH1 and GLI1 was 64.8%, 46.5%, and 54.9%, respectively." (PMID 25811359, 2015). "For example, in one study of xenografted tumors, GLI1 mRNA localized to the stromal compartment while SHH localized to the prostatic epithelium, indicating active paracrine Hh signaling from the tumor in the surrounding stroma." (PMID 26426053, 2015). "SMO inhibition alters transcription factors GLI1 and GLI2 to remain inactive, which prevents the expression of tumor mediating genes within the Hh pathway." (PMID 25985215, 2015). "Since Hh signaling plays a critical role in mammary stem cell maintenance within the mammary epithelium, it is not surprising that mammary CD44+/CD24−/lowLin− CSCs express increased mRNA transcript levels of PTCH1, GLI1 and GLI2 compared to bulk tumour cells." (PMID 26270676, 2015). "Specifically, in panels D, a Gli1 molecule and a GLI2 molecule had weak expressions; the expressions of E-cadherin and SMAD-7 were significantly increased in the tumor areas, and the differences were statistically significant." (PMID 25895132, 2015). "It was demonstrated that elevated GLI1 in these mice abrogates ATR-CHK1-signaling, induces spontaneous and IR-induced genome instability and promotes tumor development." (PMID 26633513, 2015). "Based on these findings, we conclude that combined GLI1/2 and PI3K/mTOR inhibition is a promising novel therapeutic approach for synergistic apoptosis induction and tumor growth reduction in RMS." (PMID 25749378, 2015).
tumor (continued). "Although there is overwhelming evidence that GLI1 plays an important role in tumor initiation and progression of several kinds of malignancies, these results suggest the transcription factor may have a tumor protective role in the later stages of certain cancers." (PMID 25352983, 2014). "Since Gli1 expression is consistently correlated with HH pathway activation, these data suggest that HH signaling is active in CD133+ cells containing tumor samples R18 and R28." (PMID 24978848, 2014). "To establish the role of GLI1 in NRP2-mediated tumour initiation, we expressed GLI1 in the SUM1315 NRP2low cells and assayed their ability to form orthotopic tumours." (PMID 23436775, 2013). "Nowadays, numerous Hh pathway inhibitors have already been developed, most of them targeting Smo, but also small molecules against Gli1/2 (GANT58, GANT61) and Shh (Robotnikinin) are currently under preclinical development in various tumor types, including PCa." (PMID 23880852, 2013). "The pathological morphology and immunohistochemistry staining revealed that liposomal SANT75 induced tumor cell apoptosis, inhibited tumor angiogenesis as assessed by CD31 and down-regulated the expression of Hh target protein Gli-1 in tumor tissues." (PMID 23560085, 2013). "Up-regulation of Smo increased transcription of Gli1 and MMP9 which led to increased tumor cell invasiveness." (PMID 23880852, 2013). "Our results show that Gli1 expression in the stroma was specifically and significantly reduced within 24 hours of IPI-926 treatment while expression of Gli1 in tumor cells was unaffected." (PMID 22140510, 2011). "Tumor-specific disturbances of alternative splicing were also found for GLI1 oncogene and CEACAM1 tumor suppressor." (PMID 21082031, 2010). "In four common samples where we observe up-regulation of Perlecan in tumor tissue, we previously detected up-regulation of SHH, PTCH1 and GLI1 (patients 945, 1854, 921 and 1866) suggesting a complete functional pathway in these tumors." (PMID 16507112, 2006). "The overarching rationale was to create a multi-faceted epigenetic panel that captures different aspects of GBM biology: DNA repair and chemoresistance (MGMT), stress response and oncogenic signaling (NUPR1), tumor suppression (NDRG2), and developmental pathway activation (GLI1)." (PMID 41596413, 2026). "Hh pathway components Gli1 and SMO were increasingly present in both tumor types, but more prominently in MIBC, suggesting a correlation between cilia-dependent Hh signaling and tumor progression." (PMID 40301543, 2025). "An immunohistochemical analysis demonstrated the expression of Patched1, Gli1, and Gli2 in 70%, 70%, and 65% of human ONB cases, respectively, with Patched1 levels inversely and Gli1 levels positively correlating with the tumor severity based on Kadish staging and Hyams grading." (PMID 40710426, 2025). "In contrast, there was no significant expression of GLI1 observed in the mammary tissues of control mice, whereas significantly increased expression of the same was evident in the tumor tissue of the tumor-bearing mice." (PMID 39880092, 2025). "RT‐qPCR and Western blot analyses showed that miR‐217 and TSHZ2 expressions were significantly increased in the tumor tissues of the Lv‐miR‐217 + oe‐NC group compared to the Lv‐NC + oe‐NC group, whereas DNMT1, SHH, and GLI1 expression were significantly decreased." (PMID 40909350, 2025). "In general GLI-1 tumours are a new emerging entity, its histological spectrum is not fully defined yet, and there is uncertainty regarding the features that makes the tumour malignant or benign." (PMID 41035732, 2025). "However, our results revealed a significant decrease in SMO and GLI‐1 protein levels in tumor tissues, suggesting that Rab23 plays a negative regulatory role in the SHH signaling pathway and can suppress tumor growth in HCC." (PMID 37884351, 2024).
tumor (continued). "LINC01093 impedes GLI1 mRNA from binding to IGF2BP1 by competitive binding to IGF2BP1, thereby inhibiting the expression of GLI1 downstream genes and playing a crucial role in restraining tumor proliferation and metastasis." (PMID 38166832, 2024). "Similar situations can arise in neoplasms with GLI1 alterations, where immunohistochemistry for GLI1 is not always sufficient, necessitating molecular confirmation." (PMID 38275873, 2024). "Conversely, GLI1 expression displayed a negative correlation with B cells (r = 0.183, p = 5.56e−5) and tumor purity (r = −0.406, p = 7.76e-14) in BRCA." (PMID 39483334, 2024). "Furthermore, in vivo studies have demonstrated that suppression of the Rab23 gene results in decreased tumor size, proliferation rate, and reduced levels of SHH‐related proteins Smoothened and GLI‐1." (PMID 37884351, 2024). "Another study identified the upregulation of circIPO11 in tumor tissues and cancer stem cells, where it activates the Hedgehog pathway by recruiting TOP1 (topoisomerase 1) to the promoter region of the transcription factor GLI1 (GLI family zinc finger 1)." (PMID 38398157, 2024). "In addition, Hedgehog‐Gli1 mediates an increase in the expression of circ‐0011536 in tumor exosomes, followed by targeting miR‐451a/VGF signaling to promote tumor growth and increase peripheral nerve invasion and remodeling in PDAC." (PMID 39584047, 2024). "Liu S.J.’s research suggests that downregulation of the Rab 23 gene may enhance apoptosis, decrease tumor size, reduce the proliferation rate, and decrease the levels of SHH-related proteins (SMO and GLI-1) in Hep 3B cells." (PMID 38730691, 2024). "Advanced HNSCC tumours were shown to express higher levels of SHH, PTCH1, SMO, GLI1, GLI2 and GLI3." (PMID 39234399, 2024). "In our results GLI1 full length (GLI1) was expressed mainly in cytoplasmic location in stroma and tumor tissue regardless of the grade group." (PMID 38370352, 2024). "Moreover, truncated GLI1 (TGLI1), a product of SHH signalling, functions as an enhanced GLI1, promoting angiogenic heparanase expression and thereby facilitating GBM angiogenesis and tumour growth." (PMID 39568072, 2024). "Additionally, SHH, GLI1, and SMO overexpression were significantly correlated with tumor recurrence and shorter disease-free survival (DFS)." (PMID 37626893, 2023). "Interestingly, the inhibition of GLI1/2 and PI3K/mTOR seems to produce a synergistic effect on apoptosis induction and tumour growth reduction in RMS." (PMID 36765685, 2023). "The fluorescence in situ hybridization (FISH) test of the tumor tissue showed no broken rearrangement of the GLI1 gene and that of the EWSR1 gene in the patient’s tumor." (PMID 37658451, 2023). "Interestingly, emerging evidence has shown that Gli1 also functions as a positive regulator of PDL1 expression, highlighting the potential importance of Hh signaling in tumor immunotherapy." (PMID 38097536, 2023). "Tumor volume and tumor weight were both reduced compared to the control group in conjunction with reduced cell proliferation and IHC signal expression of SMO, PTCH1, and GLI1." (PMID 36986819, 2023). "At baseline non-irradiated tumor cells engineered to ectopically express GLI1 demonstrate a 1.5-fold increase in RNA Pol I activity." (PMID 37380890, 2023). "An intraperitoneal administration of GANT61 (40 mg/kg), a small-molecule inhibitor of Gli1 and Gli2, resulted in significant inhibition of cortical bone destruction, TRAP-positive osteoclasts within the cortical bone, and endomucin-positive tumor vessels." (PMID 37240209, 2023). "We present novel evidence that in these irradiated tumor cells, Treacle ribosome biogenesis factor 1 (TCOF1), a nucleolar protein that is important in ribosome biogenesis, facilitates nucleolar translocation of GLI1." (PMID 37380890, 2023).
tumor (continued). "In conclusion, our studies demonstrate for the first time that GLI inhibitor (Gant61), but not SMO inhibitor (LDE225), shows a potent inhibitory effect on LMS tumor growth and concomitantly suppresses the expression of GLI1- and GLI-targeted genes using the xenograft model of uterine LMS." (PMID 34642915, 2022). "Conversely, rBCCs without SCC-like features lack LY6D expression but maintain GLI1 levels throughout the tumor." (PMID 36473848, 2022). "ATO has been tested as a GLI1 inhibitor in some tumor types, such as small cell lung carcinoma, but not in OSCC." (PMID 36552049, 2022). "Because GLI1 and GLI2 facilitate the propagation of cells with damaged DNA, their expression may be naturally higher in cells that form the earliest precursor tumor lesions." (PMID 35505292, 2022). "Noncanonical activation of GLI1 and GLI2 often occurs through crosstalk with other pathways driven by oncogenic drivers or loss of tumor suppressors." (PMID 36010600, 2022). "Moreover, the expression levels of SET7/9 and Gli1 showed a positive relationship in NSCLC tumor samples, indicating a regulatory role of the SET7/9-Gli3-Gli1 axis in NSCLC development." (PMID 35069908, 2022). "It was shown that ES-derived tumor cells can exploit both GLI1 and GLI2, which may minimize the effect of GLI1 inhibitors." (PMID 35454895, 2022). "A Phase 2, open-label, placebo-controlled trial of topical itraconazole 0.7% gel applied for 1–3 months in BCC treatment did not yield reduction of GLI1 mRNA expression or tumor size." (PMID 35954384, 2022). "In the mouse model of PDAC, SMO-independent GLI1 activation promotes transformation and requires both TGFβ and KRAS signaling where inhibition of TGFβ by TbRI antagonist SD208 significantly reduces tumor burden and increases infiltration of lymphocytes." (PMID 34113570, 2021). "Furthermore, IHC assays revealed that GNG7 overexpression resulted in distinct suppression of Hedgehog signaling pathway-related molecules (GLI1, PTHCH1 and SMO) in tumor tissues obtain from xenograft tumor model." (PMID 34635014, 2021). "To verify whether GLI1 overexpression upregulates cell cycle regulators and the PI3K/AKT pathway in this model, we examined the expression of GLI1, p-AKT, Cyclin D3, CDK4, and Ki67 in the xenograft tumor tissues using immunohistochemical staining." (PMID 33658491, 2021). "In our research, the correlation coefficients between Gli1 and NF-κB, Shh and NF-κB were only slightly over 0.5 in PDAC tissues, and this may be due to inter- and intra-tumor heterogeneity." (PMID 34046348, 2021). "The optimization of cyclopamine, by addition of a glucuronide group, showed a decrease in the tumor mass without having the toxic effects of Gli1 inhibition in astrocytes." (PMID 33918704, 2021). "Both PTCH1 and GLI1 were observed in more than 50% of tumor tissues, and a higher ratio of GLI1 mRNA in HCC/noncancerous liver was significantly correlated with recurrence and short overall survival (OS)." (PMID 33440657, 2021). "Taken together, these data strongly support a transcription-dependent tumor-suppressive role for GLI1 in the more frequent NB cases not harboring MYCN amplifications." (PMID 33921042, 2021). "Moreover, combined administration of GLI1 inhibitor and DDP led to impaired tumor growth in the mouse model." (PMID 34659557, 2021). "Interestingly, when LNCaP-AI cells were grown as spheroids, a more biologically relevant model of tumor growth, SHH expression increased while PTCH1 and GLI1 remained unchanged." (PMID 34290270, 2021). "In contrast, these key Hh pathway components were found to be significantly over-expressed in VSCC compared to normal vulval epithelium: SHH (median 1.0), PTCH1 (median 2.0), GLI1 (median 3.5) and GLI2 (median 3.5), and their expression were uniformly distributed across the tumour." (PMID 34480080, 2021). "However, canonical SMO-dependent SHH signaling, as mediated by GLI1 nuclear localization, downregulates WNT signaling and tumor cell differentiation." (PMID 31979397, 2020).
tumor (continued). "The protein expression of CysLT2R and 15-PGDH in matched normal vs tumour tissue showed a negative correlation with GLI1 expression." (PMID 32814764, 2020). "We did not identify a single neoplasm for which GLI1/2 expression was correlated with that of HH genes without a simultaneous correlation with that of at least one of the TGFB genes." (PMID 32879407, 2020). "Interestingly, quantitative PCR analysis indicates that the expression of gli1 and AKT genes by tumor cells from mice biopsies and from cultured cells are upregulated when YAP able to interact with TEAD is over-expressed." (PMID 33419295, 2020). "Furthermore, GLI1 expression was positively correlated with stemness and negatively correlated with differentiation in CRC patients when comparing tumour and mucosal tissues." (PMID 32814764, 2020). "We next analysed the mRNA expression levels in tumour and adjacent mucosa samples from 17 paired CRC patients, which also suggested a significantly positive correlation between GLI1 and the stemness markers DCLK1 and LGR5 with elevated expression of all three genes in tumour tissues." (PMID 32814764, 2020). "Independent of tumor stage, the expression ratio of GLI1/NBS1 was consistently in the range of 1.3–1.4." (PMID 32185127, 2020). "Results of IHC and Western blots showed a remarkably decreased expression of Gli1 protein in tumors derived from HCT116 cells stably expressing AIM2, suggesting Gli1 may be involved in tumor growth regulated by AIM2 in CRC." (PMID 33291082, 2020). "Similar to GBM, tGLI1 is expressed in a tumor specific pattern, i.e., observed only in malignant breast tissue and cells, and transactivates novel target genes not regulated by GLI1 to promote aggressive phenotypes." (PMID 32957513, 2020). "Aberrant activation of the Hh signaling pathway by mutations in pathway components such as PTCH, SUFU, SMO, and amplifications of GLI1 and GLI2 drive tumor growth in basal cell carcinoma (BCC), medulloblastoma, keratocystic odontogenic tumors, meningioma, and ameloblastoma." (PMID 32108165, 2020). "Here, we demonstrate potent anti-tumor effects after dual PI3K/mTOR inhibition that may be mediated, at least in part, by disrupting nuclear GLI1." (PMID 31492956, 2019). "Based on the date presented herein, the expression levels of GLI1 and PTCH1were observed only in the nucleus of the tumor cells during in situ hybridization, but no expression was found in the surrounding stromal cells." (PMID 30769952, 2019). "This is revealed by infrequent and weak expression of GLI1 in single tumor areas in 50% of cSCC and by the absence of cSCC growth changes upon GLI1 downregulation." (PMID 31867038, 2019). "The lack of tumor formation in Gli1-CreERT; Ptch1f/f mice suggests that activation of Hh signaling in MSCs but not in chondrocytes or osteoprogenitors promotes tumorigenesis." (PMID 31482846, 2019). "Moreover, it keeps tumor growth local through repression of pro-metastatic TMED9-TGFα signaling via its downregulation of TMED9, CNIH4, TGFA, and GLI1." (PMID 31253868, 2019). "Examination of Hh transcripts indicate that tumor growth suppression correlates with down-regulation of GLI1, PTCH1, and SMO transcripts in cells of mouse but not of human origin." (PMID 31658643, 2019). "It has been reported that GLI1 and GLI2 play important roles in tumor development and progression." (PMID 31783569, 2019). "In ER-positive BC, increased GLI1 expression correlated with early disease onset, increased SHH expression, high Ki-67 index, higher histological grade, advanced tumor stage, lymph node involvement, metastasis, and shorter overall survival and disease-free survival." (PMID 31027259, 2019). "Nevertheless, it is important to point out that GLI1 is a bone fide target in some tumours regardless of its role in the HH pathway." (PMID 30068568, 2018).